PABPC4 (poly(A) binding protein cytoplasmic 4)
Description:
Binds the poly(A) tail of mRNA. Binds to SMIM26 mRNA and plays a role in its post-transcriptional regulation. May be involved in cytoplasmic regulatory processes of mRNA metabolism. Can probably bind to cytoplasmic RNA sequences other than poly(A) in vivo (By similarity).
Synonyms: APP-1; iPABP; APP1; PABP4
Tractability: PROTAC: UniProt records ubiquitination sites on it; ubiquitination databases record sites on it; its protein half-life has been measured.
Gene: Protein-coding gene on chromosome 1 (39,560,709 to 39,576,868, reverse strand). Ensembl gene ENSG00000090621.
Subcellular location: Cytoplasm
Subcellular location (Human Protein Atlas): Cytosol
Gene Ontology:
Molecular function: poly(A) binding; poly(C) RNA binding; poly(U) RNA binding; protein binding; RNA binding; mRNA 3'-UTR binding; nucleic acid binding
Biological process: blood coagulation; RNA catabolic process; RNA processing; translation
Cellular component: cytoplasm; cytoplasmic stress granule; cytosol; nucleus; ribonucleoprotein complex
Genetic constraint (gnomAD): Loss-of-function variants: 14 observed, 70.38 expected, observed/expected ratio (o/e) 0.2, 90% interval 0.13 to 0.31. The upper end of that interval is the gene's LOEUF score, 0.31, which puts it in group 1 of 6, group 1 being the genes least tolerant of losing a copy. Missense variants: 579 observed, 842.68 expected, observed/expected ratio (o/e) 0.69, 90% interval 0.64 to 0.74. Synonymous variants: 328 observed, 303.12 expected, observed/expected ratio (o/e) 1.08, 90% interval 0.99 to 1.19.
Homologues: Orthologues: chimpanzee PABPC4 (100% identical), macaque PABPC4 (99% identical), guinea pig PABPC4 (99% identical), pig PABPC4 (99% identical), rat Pabpc4 (98% identical), dog PABPC4 (96% identical), mouse Pabpc4 (93% identical), rabbit PABPC4 (91% identical), rat Pabpc4-ps1 (83% identical), zebrafish pabpc4 (82% identical), tropical clawed frog pabpc4 (82% identical). Paralogues in human: PABPC1 (75% identical), PABPC3 (69% identical), PABPC1L (64% identical), PABPC4L (42% identical), PABPC5 (37% identical), PABPC1L2A (23% identical), PABPC1L2B (23% identical), RBMS3 (16% identical), SYNCRIP (16% identical), RBMS1 (16% identical), HNRNPR (15% identical), RBMS2 (15% identical), and 12 more.
Diseases named in the same sentence as PABPC4 in open-access papers:
PABPC4 is named in the same sentence as 41 diseases in open-access papers, as found by Europe PMC text mining. Sharing a sentence is not in itself a finding about the gene and the disease. The quoted sentences say what the papers report.
breast carcinoma (4 papers, 2012 to 2024). "In line with PABPC4 acting together with HNRNPC, lower PABPC4 expression was associated with worse prognostic metrics and disease progression in breast cancer patient cohorts." (PMID 37156909, 2023). "We have uncovered an intricate gene regulatory programme at the intersection of APA and translational control mediated by HNRNPC and PABPC4 that plays a metastasis suppressing role in breast cancer." (PMID 37156909, 2023). "The most significant differences in expression pattern were revealed for RAD50 and LGALS3BP in different histological types of breast cancer and for PABPC4 and FAM50A antigens in immune cells infiltrating breast tumors." (PMID 23181716, 2012). "The most significant differences in expression pattern were revealed for RAD50 and LGALS3BP in cancer cells of different histological types of breast cancer and for PABPC4 and FAM50A antigens in immune cells infiltrating breast tumors." (PMID 23181716, 2012). "Despite silico-derived data being obtained from a small number of patients, we were able to identify ALDH1A3, MED20, PABPC4, SLC26A11 and SCP2 as deregulated genes in diabetic breast cancer patients, which coincided with our microarray data." (PMID 37511575, 2023). "In current study we analyzed six previously identified medullary breast carcinoma autoantigens including LGALS3BP, RAD50, FAM50A, RBPJ, PABPC4, LRRFIP1 with cancer restricted serological profile in different histological types of breast cancer." (PMID 23181716, 2012). "This pilot study made possible to select 4 antigens LGALS3BP, RAD50, PABPC4, and FAM50A as promising candidates for more comprehensive research as potential molecular markers for breast cancer diagnostics and therapy." (PMID 23181716, 2012). "Another study on breast cancer described LIN28A interactions with hnRNP A1, DDX3, Ku70, and PABPC4." (PMID 38976670, 2024). "Thus, during this study we described for the first time expression patterns of 6 potential MBC-associated antigens, including LGALS3BP, RAD50, FAM50A, RBPJ, PABPC4, LRRFIP1 in different histological types of breast carcinomas and non-cancerous breast tissues by immunohistochemical analysis." (PMID 23181716, 2012).
type 2 diabetes (4 papers, 2016 to 2025). "The chromosome 1 MACF1‐HEYL signal region includes PABPC4 which has been implicated in type 2 diabetes through an effect mediated through visceral adipose tissue." (PMID 40538118, 2025). "At the 1p34.3 locus, genetically elevated expression of PABPC4 was associated with decreased type 2 diabetes risk." (PMID 37540242, 2023). "Ten VAT-specific candidate genes were associated with type 2 diabetes after Bonferroni correction, including five causal genes supported by SMR and co-localisation: PABPC4 (1p34.3); CCNE2 (8q22.1); HAUS6 (9p22.1); CWF19L1 (10q24.31); and CCDC92 (12q24.31)." (PMID 37540242, 2023). "For example, PABPC4 mediated the impact of cg15123755-HDL on type-2 diabetes." (PMID 37274792, 2023). "According to the analysis of bulk RNA-seq data, three significantly differentially expressed TWAS-identified genes were observed when comparing individuals with type 2 diabetes and non-diabetic individuals with morbid obesity: PABPC4 (p=0.004); HAUS6 (p=0.011); and DNLZ (p=0.013)." (PMID 37540242, 2023).
COVID-19 (3 papers, 2021 to 2023). A disease caused by infection with severe acute respiratory syndrome coronavirus 2. "We focused on the impact of VKORC1, SERPING1, and PABPC4 gene variants on COVID-19 severity." (PMID 33730015, 2021). "Similarly, PABPC1 and PABPC4 have been recently identified as downregulated COVID-19-altered proteins, both of which are known autoantigens, offering a possible explanation for the autoimmune complications observed in COVID-19 patients." (PMID 36835058, 2023). "To study the role of coagulation in COVID-19 pathogenesis, we explored the interactions of VKORC1, SERPING1 and PABPC4 with viral proteins through computational docking." (PMID 33730015, 2021). "Furthermore, pharmacological modulation of the PABPC4-MARCH8-NDP52 autophagosome pathway might serve as a practical strategy for treating CoV infections, especially for COVID-19." (PMID 34612687, 2021).
hepatocellular carcinoma (3 papers, 2022 to 2024). A malignant tumor that arises from hepatocytes. "circFAM134B as a regulator of ER-phagy-mediated ferroptosis in hepatocellular carcinoma (HCC) by sponging PABPC4 to stabilize FAM134B mRNA, enhancing the effectiveness of lenvatinib treatment through increased ROS and Fe2+ levels." (PMID 39315094, 2024). "For example, lncRNA RP11-286H15.1 binds to PABP cytoplasmic 4 (PABPC4) and promotes its ubiquitination, thus reducing the stability of tripartite motif-containing protein 37 (TRIM37) and cell division cycle protein 27 (CDC27) mRNAs in hepatocellular carcinoma (HCC) cells." (PMID 37225681, 2023).
prostate carcinoma (3 papers, 2021 to 2024). A carcinoma that arises from epithelial cells of the prostate gland. "PABPC4, a protein kinase, may be a valuable source of biomarkers for response to docetaxel-resistance prostate cancer therapy." (PMID 33880366, 2021).
viral infection (3 papers, 2017 to 2024). "Additionally, BNIP3L was elevated in bacterial infection, potentially reflecting its role in mitophagy, while DNMT1, IFI27, SLFN5, and AHNAK were elevated in viral infection, and PABPC4 was elevated in KD." (PMID 39240972, 2024). "Cells were transfected with PABPC4-FLAG for 24 h and infected with Betacoronavirus (MHV), Gammacoronavirus (IBV), or Deltacoronavirus (PDCoV) to investigate whether PABPC4 regulates the levels of N protein during viral infection." (PMID 34612687, 2021). "However, the antiviral function of PABPC4 and the regulation mechanism of PABPC4 during virus infection remains unexplored." (PMID 34612687, 2021). "Poly(A)-binding protein 4 (PABPC4), one of the homologs of PABP, was initially identified as a human T-cell activation-induced protein, but its role in cellular processes and virus infection has not been further explored." (PMID 34612687, 2021).
breast tumors (2 papers, 2012 to 2020). "For PABPC4, it exhibited significant differences in expression in immune cell-infiltrating breast tumors, hopefully regarding as a candidate for its diagnostics and therapy." (PMID 32454908, 2020). "Moreover, antigens FAM50A and PABPC4 are intriguing targets for investigation of the features of the immune response in patients with highly infiltrating breast tumors including MBC, which despite anaplastic features has favorable prognosis." (PMID 23181716, 2012). "Additionally increased expression of other antigen PABPC4 was observed in restricted number of immune cells infiltrating breast tumors." (PMID 23181716, 2012).
diabetes (2 papers, 2023 to 2024). "For example, instruments are from genes TCF7L2, IGF2BP2, NOTCH2, CDKAL1, PABPC4, FTO and JAZF1, known to be associated with diabetes and that have been further significantly associated with the metabolites." (PMID 39349772, 2024).
anaplastic large cell lymphoma (1 paper, 2021). Anaplastic large cell lymphoma (ALCL) is a rare and aggressive peripheral T-cell non-Hodgkin lymphoma, belonging to the group of CD30-positive lymphoproliferative disorders, which affects lymph nodes and extranodal sites. "Numerous genomic rearrangements were discovered in human anaplastic large cell lymphoma (ACLC) patients with an RNAseq screen, including two fusions of TYK2 to nuclear factor of kappa light polypeptide gene enhancer in B cells 2 (NFκB2) or poly(A) binding protein cytoplasmic 4 (PABPC4)." (PMID 34439323, 2021).
Burkitt lymphoma (1 paper, 2025). A rare form of malignant mature B-cell non-Hodgkin lymphoma. "Next, we constructed PABPC4-knockdown cell lines from the DLBCL cell line SU-DHL4 and the Burkitt lymphoma cell line Daudi." (PMID 41208958, 2025).
central precocious puberty (1 paper, 2021). "Here we reported that the three members of PABPs, including PABPC1, PABPC3 and PABPC4, were identified as novel substrates for MKRN3, whose deletion or loss-of-function mutations were genetically associated with human central precocious puberty (CPP)." (PMID 33744966, 2021).
cervical cancer (1 paper, 2022). A primary or metastatic malignant neoplasm involving the cervix. "This highlighted that PABPC4 specifically could impact the levels of hTERT mRNA, despite being expressed at less than 10% of the amount of PABPC1 in cervical cancer cell lines." (PMID 35891463, 2022). "Therefore, PABPC1 and PABPC4 were knocked down by shRNA in C33A cells, a cervical cancer cell line that does not contain HPV." (PMID 35891463, 2022).
colon cancer (1 paper, 2021). "PABPC4, a Poly (A)-binding protein, is expressed at a higher level in colon cancer and lung adenocarcinoma compared to normal tissues." (PMID 34012913, 2021).
hepatitis C (1 paper, 2021). "PABPC4, another associated protein of Lnc-PCIR, which has been demonstrated related to the inflammatory biomarker (C-reactive protein) and anti-hepatitis C response, is expressed at a higher level in tumor tissues." (PMID 34012913, 2021).
HIV-1 infection (1 paper, 2019). The type species of lentivirus and the etiologic agent of acquired immunodeficiency syndrome (AIDS). "Interestingly, PABPC4, a downregulated gene by HIV-1 infection, harbors the ability to suppress HIV-1 production." (PMID 30915053, 2019).
hypogonadism (1 paper, 2025). A disorder characterized by decreased function of the gonads. "NYNRIN, TUFM, and SH2B1 were uniquely identified by colocalization analysis of hypogonadism, while NF1, PABPC4, and SHROOM3 were uniquely identified through colocalization analysis of total testosterone." (PMID 40316537, 2025).
Insulin resistance (1 paper, 2023). Increased resistance towards insulin, that is, diminished effectiveness of insulin in reducing blood glucose levels. "Moreover, the decreased Pparg expression suggested that Pabpc4 may be involved in pre-adipocyte differentiation, which has been shown to be related to adipocyte insulin resistance." (PMID 37540242, 2023).
lung carcinoma (1 paper, 2021). "The positive mode has marker traits pulmonary function and the C-reactive protein, and the few markers genes (IL6R, ARHGAP10, BCL7B, PABPC4) are also involved in immune response and lung cancer progression." (PMID 34157017, 2021).
sarcopenia (1 paper, 2025). Progressive decline in muscle mass due to aging which results in decreased functional capacity of muscles. "These analyses highlighted SLC25A12 and PABPC4 as potential crucial diagnostic biomarkers for sarcopenia." (PMID 41463417, 2025). "Diagnostic performance analysis demonstrated strong predictive value for SLC25A12 (AUC = 0.879) and PABPC4 (AUC = 0.858), and RT-qPCR confirmed their downregulation in the sarcopenia cell model (p < 0.01)." (PMID 41463417, 2025). "In conclusion, SLC25A12 and PABPC4 are promising biomarkers linking copper metabolism dysregulation with sarcopenia, offering potential targets for diagnosis and therapy." (PMID 41463417, 2025). "Although direct evidence linking PABPC4 to structural or functional regulation of skeletal muscle cells is lacking, its role in mitochondrial homeostasis, energy metabolism, and stress responses suggests a potential relevance to sarcopenia." (PMID 41463417, 2025).
infection (5 papers, 2021 to 2025). The state of being infected such as from the introduction of a foreign agent such as serum, vaccine, antigenic substance or organism. "In this study, we first found that the endogenous expression of PABPC4 was significantly inhibited by infection with SADS-CoV." (PMID 40266995, 2025). "Despite some small differences between cell lines, we found a strong correlation between half-life changes observed during infection of Calu-3 cells and those observed upon PABPC1 and PABPC4 knockdown in HeLa cells (Rs = 0.51)." (PMID 41279592, 2025). "We characterized the ubiquitination of the most enriched TRIM25 interactors, G3BP and UPF1, as well as two TRIM25-R54P specific interactors during infection, NME1, and PABPC4." (PMID 36067236, 2022). "In a word, the interaction between PABPC4, SERP1, and ORFV ORF047 will provide several pieces of information on ORFV infection and replication." (PMID 33499896, 2021). "Porcine kidney cells (LLC-PK1) and Vero cells were infected with PEDV (strain JS-2013) at an multiplicity of infection (MOI) of 1, and the cell lysates were analyzed using quantitative real-time PCR (qRT-PCR) to confirm the expression of PABPC4." (PMID 34612687, 2021). "Therefore, we speculated the interaction between PABPC4 and ORF047 might have an important effect on ORFV infection and replication." (PMID 33499896, 2021).
tumor (5 papers, 2012 to 2025). "Knockdown of PABPC4 significantly inhibited cell proliferation, reduced colony formation, and delayed tumor growth in vivo." (PMID 41208958, 2025). "We generated stable PABPC4-knockdown cell lines via the CRISPR-Cas9 system, and both in vitro and in vivo studies demonstrated that the overexpression of PABPC4 promoted tumor proliferation." (PMID 41208958, 2025). "One may be speculated that PABPC4 expression can be restricted to activated T cells at least in MBC tumors, and possibly contributes to a more effective immune response that can be associated with good prognosis for patients with this tumor type." (PMID 23181716, 2012). "Our findings suggest that Lnc-PCIR promotes tumor growth and metastasis via up-regulating the mRNA/protein level of TAB3 and PABPC4, activating TNF-α/NF-κB signaling pathway in TNBC." (PMID 34012913, 2021).
cancer (4 papers, 2012 to 2024). A tumor composed of atypical neoplastic, often pleomorphic cells that invade other tissues. "The colorectal cancer related protein PABPC4 of the SARS-CoV-2 interactome interacts with YWHAQ, YWHAZ & TNFRSF10D that all involve Apoptosis59." (PMID 36463386, 2022). "Increased expression of PABPC4 increases multiple cancer stem cell populations and cancer stem cell-related features in HCC cells." (PMID 36503519, 2022). "Moreover, PABPC4 showed more intensive cytoplasmic staining of immune cells compared with cancer and normal cells, as well as nuclear antigen with unknown function FAM50A." (PMID 23181716, 2012). "Regarding the clustering by rows (RBPs), there are two main clusters: the first one (mostly related to AS alterations in adult cancer), the bottom cluster in the plot, includes relevant cancer genes such as MKRN1, DKC1, or PABPC4." (PMID 39595158, 2024). "The presence of PABPC4 and MKRN1 has been observed as the most frequently enriched RBPs in the different types of cancer coherently with the literature, proving the relevance of this approach." (PMID 39595158, 2024). "In our study, we observed moderate to strong PABPC4 positive staining in cytoplasm in the most of cancer and normal cells of all tissue samples and in part of immunocytes." (PMID 23181716, 2012).
metabolic disease (1 paper, 2023). A congenital disorder (due to inherited enzyme abnormality) or acquired (due to failure of a metabolically important organ) disorder resulting from an abnormal metabolic process. "Therefore, this new metabolic interface mediated by a physical interaction between PABPC4 and NCoR1 may provide new insights for targeting metabolic disorders." (PMID 37059182, 2023).
PABPC4 also shares sentences with these, for which no sentence is quoted: liver cancer (3 papers); colorectal cancer (2); anemia (1); bacterial infection (1); celiac disease (1); Crohn disease (1); fibrocystic disease (1); leukemia (1); lung adenocarcinoma (1); medullary breast carcinoma (1); melanoma (1); morbid obesity (1); psoriatic arthritis (1); renal carcinoma (1); rheumatoid arthritis (1); triple-negative breast carcinoma (1); type 1 diabetes (1); ulcerative colitis (1).